HTT (huntingtin)
Diseases named in the same sentence as HTT in open-access papers (continued):
Sharing a sentence is not in itself a finding about the gene and the disease.
epilepsy (3 papers, 2021 to 2023). A brain disorder characterized by episodes of abnormally increased neuronal discharge resulting in transient episodes of sensory or motor neurological dysfunction, or psychic dysfunction. "Examination of the mechanism underlying huntingtin’s ability to modulate the frequency of this seizure disorder indicated that over-expression of full length HTT can promote neuronal survival following seizures." (PMID 37199581, 2023). "Given the clear impact of full-length huntingtin levels on the development of the FSDS epilepsy phenotype, we next examined possible mechanisms by which HTT provides protection." (PMID 37199581, 2023). "To evaluate the potential role of huntingtin in preventing the development of epilepsy, we utilized an idiopathic seizure disorder model identified in our laboratory." (PMID 37199581, 2023). "Our results show that the levels of huntingtin expression modulate the frequency of the FSDS phenotype, indicating that huntingtin can protect against seizure disorders, at least partially due to its ability to reduce seizure-induced neurodegeneration." (PMID 37199581, 2023). "To investigate the role of Htt in the development of epilepsy in mice, we examined the effect of altering huntingtin levels on an idiopathic seizure disorder that occurs in FVB/N mice." (PMID 37199581, 2023). "Overall, our results demonstrate a protective role for huntingtin in this form of epilepsy and provide a plausible explanation for the observation of seizures in the juvenile form of HD, Lopes-Maciel-Rodan syndrome, and Wolf-Hirschhorn syndrome." (PMID 37199581, 2023). "This work suggests the possibility that protective strategies aimed at increasing the levels of full-length huntingtin may be beneficial in some forms of epilepsy." (PMID 37199581, 2023). "Top upstream terms and network from the IPA analysis were HTT, NR4A1, CNTF, epilepsy, dyskinesia, synaptic depression, the organization of cells, and catalepsy." (PMID 36289639, 2022).
Friedreich ataxia (3 papers, 2017 to 2023). An inherited condition that affects the nervous system and causes movement problems. "However, the reports of AA9 lacking, AA9 protects the healthy medium spiny neurons in rat corticostriatal brain slices from huntingtin‐induced cell death and oligodendrocytes from cystine deprivation and reduces human and mouse cellular models of Friedreich ataxia with hallmarks of ferroptosis." (PMID 36852441, 2023).
glioma (3 papers, 2014 to 2025). A benign or malignant brain and spinal cord tumor that arises from glial cells (astrocytes, oligodendrocytes, ependymal cells). "This connection extends to glial cell models expressing α-synuclein, tau, or mutant huntingtin exon 1, suggesting a potential role for SUMO1 in lysosomal function in the context of glioma-associated protein aggregation." (PMID 38801243, 2024). "Expression of HNF4α was higher in tumors samples than controls; Huntingtin and c-Myc were found to be overexpressed in high-grade gliomas." (PMID 25050814, 2014). "14-3-3ζ, HNF4α and Huntingtin were widely expressed in glioma samples." (PMID 25050814, 2014).
heart failure (3 papers, 2013 to 2017). Inability of the heart to pump blood at an adequate rate to meet tissue metabolic requirements. "Huntington’s disease (HD), caused by expanded Huntingtin protein’s polyglutamine (PolyQ) repeats, is associated with both cardiovascular events including heart failure and amyloid-like inclusions, and heart failure causes high mortality among HD patients." (PMID 27904993, 2017). "To test the hypothesis that mutant HTT leads to heart failure through compensatory remodelling as a consequence of cellular dysfunction, we used two well-established HD mouse models." (PMID 25101683, 2014). "Huntingtin protein is expressed in many tissues including the heart and epidemiological studies suggest that HD patients have a higher susceptibility to cardiac failure compared to age-matched controls without HD." (PMID 24367279, 2013).
pheochromocytoma (3 papers, 2013 to 2021). "The first model used was a PC12 cell line (derived from rat pheochromocytoma) that expresses an inducible EGFP-tagged exon 1 of huntingtin with 23 or 74 polyglutamine repeats (Q23 or Q74)." (PMID 26268247, 2015). "Mutant huntingtin inhibits the activation of Akt induced by epidermal growth factor stimulation in rat pheochromocytoma cells." (PMID 23300147, 2013). "We used neuronal (PC12) cell lines derived from rat pheochromocytoma that express an inducible enhanced green fluorescent protein (EGFP)-tagged HTT exon 1 fragment with 23 (HD-Q23) or 74 (HD-Q74) glutamine repeats that shape the non-mutant and mutant form of HTT, respectively." (PMID 34681268, 2021).
retinal degeneration (3 papers, 2007 to 2012). Degeneration of the retina. "Mutant huntingtin is also expressed in the retinas of R6/2 and R6/1 mice, which leads to pronounced vision deficiencies and retinal degeneration." (PMID 22956270, 2012). "Adult flies expressing an expanded N-terminal fragment of human huntingtin (N-Htt128Q) in the eye show a progressive retinal degeneration which becomes obvious at day 5 after eclosion." (PMID 18166084, 2007). "This huntingtin effect cannot be observed unless the background strain does not contain the rd mutation responsible for retinal degeneration (see “Mouse genetic background”)." (PMID 22956270, 2012).
type 2 diabetes (3 papers, 2016 to 2024). "Recent work suggests that treating invertebrate and mice HD models with metformin, a well-known AMPK activator which is used worldwide to treat type 2-diabetes, reduces mutant huntingtin from cells and alleviates many of the phenotypes associated to HD." (PMID 28632780, 2017). "The primary cause for Huntington, Parkinson, Alzheimer, diabetes type 2 and Creuzfeld-Jajobs diseases, is the accumulation in, and outside cells of various misfolded conformers of specific proteins, such as huntingtin, Ataxin, alfa-synuclein, tau, insulin and PRPsc, respectively." (PMID 27508340, 2016). "Hence, metformin in HD patients is able to function in a range of pathways (e.g. on glycaemia to alleviate type 2 diabetes, on autophagy to clear out mutant huntingtin, etc.)to improve cognitive function." (PMID 28632780, 2017).
Adult onset (2 papers, 2012 to 2014). Onset of disease manifestations in adulthood, defined here as at the age of 16 years or later. "Huntington's disease (HD) is an adult-onset neurodegenerative disorder caused by expansion of a CAG repeat in the gene encoding the huntingtin (Htt) protein." (PMID 24567701, 2014).
brain tumor (2 papers, 2011 to 2014). "Overexpressed Trip10 was associated with endogenous Cdc42 and huntingtin in IMR-32 brain tumor cells and CP70 ovarian cancer cells." (PMID 21299869, 2011). "Taken together, our findings provide first evidence of function of Huntingtin in brain tumors, thus paving novel avenues of investigation on GBM pathophysiology." (PMID 25050814, 2014).
glioblastoma (2 papers, 2014 to 2019). The most malignant astrocytic tumor (WHO grade IV). "It has recently been shown that glioblastoma-derived exosomes successfully uptake modified siRNAs targeting Huntingtin mRNA and efficiently delivered siRNAs to mouse neurons and led to silence Huntingtin mRNAs." (PMID 31291956, 2019). "We discovered a novel glioblastoma control module centered on four major network hubs: Huntingtin, HNF4α, c-Myc and 14-3-3ζ." (PMID 25050814, 2014). "Moreover, exosomes exogenously enriched with siRNAs to inhibit diseases, for example, it has recently been shown that exosomes purified from glioblastoma cells can uptake synthetic siRNAs targeting Huntingtin mRNA and proficiently carried siRNAs to mouse neurons to bock Huntingtin mRNAs." (PMID 31291956, 2019).
iron deficiency (2 papers, 2014 to 2018). "Huntingtin knockdown in zebra fish results in an iron deficiency phenotype during development, and deletion of the huntingtin gene increases significantly the expression of iron uptake protein TfR, suggesting that huntingtin is implicated in iron homeostasis." (PMID 30002810, 2018). "Genetic mouse models of HD that transgenically overexpress mutant huntingtin accurately recapitulate the elevated levels of brain iron in the disease and huntingtin knockdown in zebra fish models result in an iron deficiency phenotype." (PMID 24795635, 2014).
oral squamous cell carcinoma (2 papers, 2020 to 2024). "Based on these results we predict that miR-146a overexpression in oral squamous cell carcinoma potentiates cancer cell migration and invasion possibly via targeting HTT." (PMID 33282738, 2020). "This study aims to explore the miR-146a expression pattern in oral squamous cell carcinoma (OSCC) and its role and mechanism in OSCC progression and metastasis via targeting the HTT gene." (PMID 33282738, 2020).
pancreatic cancer (2 papers, 2014 to 2021). "Huntingtin transcript HTT-202 is non-canonical and we found it down-regulated in pancreatic tumors." (PMID 34316711, 2021).
retinitis pigmentosa (2 papers, 2013 to 2023). Retinitis pigmentosa (RP) is an inherited retinal dystrophy leading to progressive loss of the photoreceptors and retinal pigment epithelium and resulting in blindness usually after several decades. "Antisense oligonucleotides (ASOs) were used for allele-specific targeting of the Huntingtin gene, and rhodopsin P23H gene in retinitis pigmentosa, where ASO-mediated silencing led to long-term effects in rodent models." (PMID 37864244, 2023).
Wolf-Hirschhorn syndrome (2 papers, 2023 to 2025). Wolf-Hirschhorn syndrome (WHS) is a developmental disorder characterized by typical craniofacial features, prenatal and postnatal growth impairment, intellectual disability, severe delayed psychomotor development, seizures, and hypotonia. "Wolf-Hirschhorn syndrome is a congenital malformation syndrome, which results from a hemizygous deletion on chromosome 4p16.3 that includes the HTT gene." (PMID 37199581, 2023).
age (1 paper, 2011). A temporal measurement of the time period elapsed since an identifiable point in the life cycle of an organism. "Secondly, we tested a yeast model for age-associated neurodegenerative disorders in which inducible CFP is fused to the first exon of huntingtin with toxic (Htt103Q) or non-toxic (Htt25Q) glutamine expansions." (PMID 21931558, 2011).
brain injury (1 paper, 2023). Acute and chronic (see also brain INJURIES, CHRONIC) injuries to the brain, including the cerebral hemispheres, CEREBELLUM, and brain STEM. "Here, we test the hypothesis that excess pathogenic huntingtin (HTT) impairs mitochondrial homeostasis, using Drosophila genetics and pharmacological inhibitors in HD and polyQ-expansion disease models and in a mechanical stress-induced traumatic brain injury (TBI) model." (PMID 37830620, 2023).
breast tumours (1 paper, 2013). "Analysis of the levels of huntingtin transcripts by quantitative real-time RT-PCR in MMTV-PyVT/HdhQ7/Q7 and MMTV-PyVT/HdhQ111/Q111 breast tumours confirmed this observation." (PMID 23300147, 2013). "Thus, mutant huntingtin is expressed in breast tumours where it may influence cancer progression." (PMID 23300147, 2013).
Cachexia (1 paper, 2017). Severe weight loss, wasting of muscle, loss of appetite, and general debility related to a chronic disease. "In a last step, we also link our results to pathological conditions by investigating carriers of the Huntingtin mutation – a disease associated with sarcopenia and cachexia that are not only due to permanent choreatiform movements but also to impairment of metabolic functions." (PMID 28819135, 2017).
channelopathies (1 paper, 2025). "For example, ATN1 and HTT have been linked to neurodevelopmental disorders, while CACNA1A has been linked to channelopathies with diverse neurological manifestations." (PMID 41254939, 2025).
cognitive (1 paper, 2013). "However, the relationship between mutant huntingtin (mhtt) aggregation and MSN loss, motor and cognitive deficits in BACHD rodent models for HD appears complex." (PMID 23874679, 2013).
gastric cancer (1 paper, 2022). A primary or metastatic malignant neoplasm involving the stomach. "Hmgb1/2 inhibits genotoxic stress in polyglutamine diseases by interacting with mutant ataxin-1 and huntingtin protein; suppressing Hmgb2 expression causes gastric cancer cells to be less sensitive to chemotherapy." (PMID 35574435, 2022).
hereditary ataxia (1 paper, 2022). An instance of an atactic disorder that is caused by an inherited genomic modification in an individual. "In patients with suspected hereditary ataxia, we identified expansions in loci that had not been assessed as part of routine diagnostic workup within the NHS at the time of recruitment, including ATN1, ATXN2, ATXN3, ATXN7, CACNA1A, FXN, TBP, and HTT." (PMID 35182509, 2022).
Hutchinson-Gilford progeria syndrome (1 paper, 2012). "Prominent examples include the nuclear lamins, which accumulate at the nuclear periphery in the premature aging disorder Hutchinson-Gilford Progeria Syndrome, or huntingtin, a protein that can pathologically misfold in the nucleus." (PMID 22363705, 2012).
Hydrocephalus (1 paper, 2025). Hydrocephalus is an active distension of the ventricular system of the brain resulting from inadequate passage of CSF from its point of production within the cerebral ventricles to its point of absorption into the systemic circulation. "Genes like cyclin O (CCNO), NME/NM23 family member 7 (NME7), and huntingtin (HTT) are also involved in centriole amplification, γ-tubulin ring complex activity, and centrosomal organization, and their disruption can cause failure in cilia development and hydrocephalus." (PMID 40722587, 2025).
Hyperglycemia (1 paper, 2016). An increased concentration of glucose in the blood. "Therefore, we hypothesize that hyperglycemia, and the unavoidable glycation of proteins including HTT, may not only be a consequence but also a contributing factor in HD pathogenesis." (PMID 27857176, 2016).
hyperprolinemia (1 paper, 2024). Hyperprolinemia is when there isan excess of a particular protein building block (amino acid), called proline, in the blood. "It would be of particular interest to learn if N-PPG induced hyperprolinemia and/or hyperhydroxyprolinemia can directly or indirectly impact either the structure or activity of other key metabolic proteins or even HTT itself." (PMID 38128812, 2024).
Lissencephaly (1 paper, 2015). A spectrum of malformations of cortical development caused by insufficient neuronal migration that subsumes the terms agyria, pachygyria and subcortical band heterotopia. "Cortical disruptions that derive from mutations in genes such as NDE1, LIS1, PP4c, WDR62, CENPE, TCOF1, AGS3, VANGL2 and HTT, are classified as micro- or macro-cephaly, and/or cortical disorganization and abnormal cortical architecture, lissencephaly and simplified gyral patterns." (PMID 25729350, 2015).
mammary adenocarcinomas (1 paper, 2013). "Examination of whole-mount mammary glands from virgin female MMTV-PyVT/HdhQ111/Q111 mice at 8, 12 and 14 weeks revealed larger mammary adenocarcinomas than in the huntingtin heterozygous condition, themselves larger than those produced in the wild-type background at the same age." (PMID 23300147, 2013).
metachromatic leukodystrophy (1 paper, 2024). A rare lysosomal storage disorder characterized by intralysosomal accumulation of sulfatides in various tissues, leading to progressive deterioration of motor and neurocognitive function. "For instance, among genetic mutations linked to known hNDDs, examples include HTT gene mutation in HD, SOD1 in amyotrophic lateral sclerosis, PSEN1, PSEN2, and APP in AD, ARSA gene mutation in metachromatic leukodystrophy (MLD), and others." (PMID 39200370, 2024).
migraine with aura (1 paper, 2021). A migraine disorder characterized by episodes that are preceded by focal neurological symptoms. "Interestingly, several genes were abundantly expressed already during iDN differentiation and associated with migraine with aura such as HTT, TOR1A but also DRD2 which suggests a putative implication in the development of neural progenitor cells." (PMID 34486248, 2021).
muscular atrophy (1 paper, 2020). The loss of muscle tissue due to inactivity or disease. "It is still matter of debate if muscular atrophy observed in HD patients and in animal models of HD is a primary muscular defect, due to high expression levels of mutant Huntingtin in the skeletal muscle, or it is a consequence of nerve degeneration." (PMID 33167595, 2020). "From all these studies emerges the notion that a correlation could be established between muscular atrophy and the presence of mutant Huntingtin aggregates, since these two phenomena often coexist." (PMID 33167595, 2020).
osteoporosis (1 paper, 2016). A condition of reduced bone mass, with decreased cortical thickness and a decrease in the number and size of the trabeculae of cancellous bone (but normal chemical composition), resulting in increased fracture incidence. "Reduced bone mineral density has been suggested to be an early feature of HD, suggesting that HD patients exhibit osteoporosis, probably as a direct effect of illness, due to the effect of mutant huntingtin on osteoclasts or osteoblasts in bone tissue or from immobility due to the disease." (PMID 26744893, 2016).
osteosarcoma (1 paper, 2019). A usually aggressive malignant bone-forming mesenchymal neoplasm, predominantly affecting adolescents and young adults. "Rather both SQ1 and SQ2 caused the accumulation of autophagic cargo in two different cell types, in human osteosarcoma U2OS cells (in which SQSTM1 became more abundant) and in rat neuronal PC12 cells (in which a mutant Huntingtin Q74 construct accumulated)." (PMID 30858361, 2019).
pancreatitis (1 paper, 2017). Inflammation of the pancreas. "We have here limited our investigation to the impact of peripheral huntingtin silencing on CNS-resident signs of disease, but new evidence suggests that complete silencing of huntingtin in adult animals leads to peripheral phenotypes, including unexpected fatal pancreatitis." (PMID 28453524, 2017).
sarcoma (1 paper, 2021). A usually aggressive malignant neoplasm of the soft tissue or bone. "Despite their different physiological functions, disease-related proteins like tau, α-synuclein, TAR DNA binding protein-43, fused in sarcoma and mutant huntingtin, all share low complexity regions that can mediate their liquid-liquid phase transitions." (PMID 34019093, 2021).
scrapie (1 paper, 2024). A fatal disease of the nervous system in sheep and goats, characterized by pruritus, debility, and locomotor incoordination. "Over the years, exosome association with pathogenic proteins with seeding capacities, such as amyloid precursor protein, α-Syn, mutant huntingtin, and scrapie isoform of the prion protein, has been cemented." (PMID 37548944, 2024).
teratoma (1 paper, 2010). A non-seminomatous germ cell tumor characterized by the presence of various tissues which correspond to the different germinal layers (endoderm, mesoderm, and ectoderm). "It expressed mutant huntingtin and stem cell markers, was capable of differentiating to neural cells, and developed teratoma in severely compromised immune deficient (SCID) mice." (PMID 20132560, 2010).